KAT7 (lysine acetyltransferase 7)
Diseases named in the same sentence as KAT7 in open-access papers (continued):
Sharing a sentence is not in itself a finding about the gene and the disease.
cognitive deficits (2 papers, 2022 to 2025). "Conversely, enzymes that facilitate gene transcription and chromatin accessibility, such as Tet1/2, Kat7, and Cbp, were downregulated following binge-like alcohol exposure, consistent with previous reports linking alcohol consumption to chromatin condensation and cognitive impairments." (PMID 41561438, 2025).
myocardial ischemia (2 papers, 2023 to 2025). A disorder of cardiac function caused by insufficient blood flow to the muscle tissue of the heart. "In addition, it relieves myocardial ischemia/reperfusion injury by suppressing autophagy via the inhibition of HMGB1 (high mobility group box 1) by repressing KAT7 (lysine acetyltransferase 7) in MI." (PMID 36975887, 2023). "Another investigation found that circFoxo3 alleviated myocardial ischemia/reperfusion injury by reducing autophagy, achieved by inhibiting HMGB1 through the suppression of KAT7 in myocardial infarction." (PMID 40045371, 2025).
Werner syndrome (2 papers, 2024). "For instance, in the first column of data, researchers have identified, through genome-wide CRISPR screening, that the gene KAT7 promotes the onset and progression of Werner syndrome." (PMID 39213392, 2024).
colorectal tumor (1 paper, 2025). "First, we investigated the expression levels of KAT7 in colorectal tumor samples and normal colorectal tissues by searching the GEO database." (PMID 39816686, 2025).
Myocardial fibrosis (1 paper, 2024). "EAT-CM through miR-134-5p/KAT7/MnSOD/catalase axis and increase in ROS intracellular levels promoted activation of cardiac fibroblasts into myofibroblasts.Knockdown of miR-134-5p limited myocardial fibrosis in vivo." (PMID 38612394, 2024).
tumor (33 papers, 2010 to 2025). "In vitro experiments demonstrated that activation of the MAPK/ERK cascade can rescue the anti-tumor effect induced by KAT7 knockdown, as evidenced by the restoration of cell viability and proliferation, as well as the suppression of apoptosis activation." (PMID 39816686, 2025). "Given the critical role of increased motility in tumor metastasis 33,34, wound-healing assays were performed in vitro to evaluate the impact of KAT7 silencing on CRC cell behavior." (PMID 39816686, 2025). "Calculating the average daily tumor growth using the formula (Tumor volume on Day 25)/25 revealed that KAT7 knockdown inhibited COLO320 xenograft growth in vivo." (PMID 39816686, 2025). "The genes Herc6, Kat7, Mef2c, Rbm15, and Shld3 were found to be upregulated in both the right and left tumors of the treated groups, suggesting a coordinated response in tumor inhibition." (PMID 39339213, 2024). "KAT7, for example, inhibits tumor cell proliferation and invasion by acetylating H4K5 at promoters of FOXO1 and FOXO3a genes, and HDAC5 loss increased H3K27-ac acetylation and circumvented oncogene-related cell cycle repression." (PMID 37789275, 2023). "Furthermore, qRT-PCR analysis of 9 crucial genes involved in tumor progression, consistent with the heatmap data, demonstrated their downregulation upon KAT7 knockdown." (PMID 39816686, 2025). "Finally, survival analysis results demonstrated that knocking down KAT7 in COLO320 cells noticeably extended the survival time of the tumor-bearing mice." (PMID 39816686, 2025). "The NLRP11/KAT7/vimentin‐K104Ac pathway may be a crucial in the inflammation‐mediated EMT in tumor cells." (PMID 37424170, 2023). "Additionally, KAT7 knockdown markedly extended the lifespan of the tumor-bearing mice." (PMID 39816686, 2025). "Moreover, KAT7 overexpression promoted tumor sphere formation, invasion, and migration but had no noticeable impact on cell proliferation, which may be because of the complex target genes of KAT7." (PMID 37424170, 2023). "Last, we evaluated the therapeutic effects of individual or combination therapy with the KAT7 inhibitor WM-3835 and the EGFR inhibitor Erlotinib on orthotopic GSC11 and GBM6 tumor xenograft models." (PMID 40678238, 2025). "Last, targeting KAT7 with a specific inhibitor or HELDR with ASOs enhances anti-GBM activity of the EGFR inhibitor, Erlotinib, in orthotopic GBM tumor xenograft models." (PMID 40678238, 2025). "The glycolytic process in the tumor microenvironment was regulated by lncRNA ENO1-IT1; a regulator of ENO1 expression, mainly via formation of the KAT7/ENO1-IT1 complex with KAT7." (PMID 37554340, 2023). "Information confirmed that the expression of KAT7 in mRNA and protein levels elevated in HCC cells leads to the proliferation and invasion of tumor cells." (PMID 37993474, 2023). "Additionally, we evaluated the effects of KAT7 on CRC growth and metastasis in vivo using mouse subcutaneous tumor and lung metastasis models." (PMID 39816686, 2025). "Our data that targeting HELDR-activated KAT7 or targeting HELDR by ASOs augments anti-GBM activity by Erlotinib validated our observation that the previously uncharacterized HELDR-KAT7 axis promotes EGFR-driven GBM tumor malignancy independent of EGFR signaling." (PMID 40678238, 2025). "In addition, KAT7 interacts with various candidate tumor suppressors although the KAT7-ARID1a interaction has not been reported until now." (PMID 36344675, 2022). "Therefore, we conclude that circMRPS35 combined with KAT7 acetylation may mediate FOXO1 and FOXO3a to interfere with tumor metastasis, laying a solid foundation for tumor intervention, which may be a major breakthrough in regulating tumors at the level of histone acetylation." (PMID 34796685, 2021). "Densitometry analysis showed that KAT6A, KAT6B and KAT7 significantly decreased in KIRC tumor tissues, but KAT5 in KIRC tumor tissues decreased to some extent, but the change was not significant." (PMID 37365518, 2023).
cancer (29 papers, 2012 to 2025). A tumor composed of atypical neoplastic, often pleomorphic cells that invade other tissues. "For cancer, clicking the “show” button reveals box plots of KAT7 expression across various types of cancer cell lines." (PMID 39213392, 2024). "We downloaded the cancer genome atlas (TCGA) data set and found that proportion of KAT7 mRNA high exhibited the highest in the KAT family." (PMID 36724120, 2023). "It is reported to interact with CDC6 and KAT7/HBO1 to regulate the cell cycle and be a cancer stem cell feature-related gene in LUAD." (PMID 34616428, 2021). "In contrast to studies in human cancer cells, KAT7 appears dispensable for DNA replication in mice embryos while being required for gene regulation." (PMID 22412942, 2012). "Although the role of KAT7 in regulating cell proliferation and apoptosis in cancer cells has been previously reported 27,45, the precise mechanisms by which KAT7 regulates CRC tumorigenesis remain unclear." (PMID 39816686, 2025). "This is due to KAT7's function in increasing the acetylation of LDHA, which in turn boosts both the proliferation and metastasis of cancer cells." (PMID 39816686, 2025). "Following the “Chemicals” section, the expression of KAT7 in cancers and noncancer diseases is presented." (PMID 39213392, 2024).
infection (5 papers, 2010 to 2024). The state of being infected such as from the introduction of a foreign agent such as serum, vaccine, antigenic substance or organism. "However, the fact that inhibition of KAT7 reverts the phenotype seen on H3K14me levels during ∆lphD infection might also imply that LphD directly modifies KAT7 acetylation." (PMID 37059817, 2023). "This revealed that inhibition of KAT7 activity abolishes the decrease in H3K14 methylation observed in infection with L. pneumophila lacking LphD (∆lphD)." (PMID 37059817, 2023).
KAT7 also shares sentences with these, for which no sentence is quoted: acute myeloid leukemia (7 papers); bladder cancer (6); non-small cell lung carcinoma (6); colon cancer (3); glioblastoma (3); glioma (3); liver cancer (3); cervical cancer (2); lung adenocarcinoma (2); lung carcinoma (2); pancreatic cancer (2); schizophrenia (2); abdominal aortic aneurysm (1); Anxiety (1); autism (1); B-cell acute lymphoblastic leukemia (1); bacterial infection (1); breast tumor (1); cerebral cavernous malformation (1); cervical (1); chronic myelomonocytic leukemia (1); chronic obstructive pulmonary disease (1); cyst (1); emphysema (1); endothelial dysfunction (1); esophageal squamous cell carcinoma (1); fibrosis (1); genetic disease (1); Huntington disease (1); Hypertrophic Obstructive Cardiomyopathy (1).
A further 13 diseases each share a sentence with KAT7 in 1 paper.